ENSG00000290578 (novel transcript)
Gene: Long non-coding RNA gene on chromosome 1 (146,320,619 to 146,409,601, reverse strand). Ensembl gene ENSG00000290578.
Gene Ontology:
Molecular function: triplet codon-amino acid adaptor activity
Biological process: translation